CRP (C-reactive protein)
Diseases named in the same sentence as CRP in open-access papers (continued):
Sharing a sentence is not in itself a finding about the gene and the disease.
infection (continued). "On the other hand, CRP and PCT did not serve as well as infection classifiers, with their AUC being non-statistically significant (0.576; 95% CI, 0.473 to 0.678; p = 0.157) and CRP (0.517; 95% CI, 0.411 to 0.623; p = 0.747)." (PMID 37296737, 2023). "The level of C-reactive protein (CRP), representing acute inflammation due to severe infection, injury, and/or chronic disease, was not completely inhibited in all types of groups but significantly recovered in the PMEZ/dEV/IM group at eight weeks." (PMID 38049879, 2023). "The most commonly studied biological markers are C-reactive protein (CRP) and procalcitonin (PCT), but both have limitations in differentiating infection from non-infection inflammatory responses after surgery." (PMID 36994432, 2023). "As expected, the standard clinical monitoring values, such as C-reactive protein (CRP) and leucocytes, were also significantly different in the intraamniotic infection group compared to women without infection during the 3 days preceding birth." (PMID 36098832, 2023). "Peripheral WBC, CRP, and ESR are typically normal in low-grade infections and afford little value in diagnosing infected nonunion." (PMID 36309703, 2022). "In our study, it is also shown that SMPP patients have higher CRP level than NSMPP patients (21 vs. 15), but not as high as an infection of bacteria." (PMID 35498793, 2022). "In general, we identified that the indicators of complete infection control were the leukocytes, neutrophils, ESR, and CRP within the normal range and no effusion and edema in the hip joint after 2 weeks of drug withdrawal." (PMID 35419459, 2022). "The laboratory results upon admission showed high CRP (205.11 mg/L), PCT (3.06 ng/mL), and IL6 (1276 pg/mL) values, suggestive of an infection, but the BALF and whole blood culture were both negative." (PMID 35847093, 2022). "Significant differences were evidenced between the two groups (documented infection and no infection) for both PCT and IL−6 (p = 0.03 and p = 0.035, respectively), but none for CRP (p = 0.1)." (PMID 36431277, 2022). "The presepsin, CRP, and PCT levels were higher in patients with infections than in those without infections (p < 0.001, p = 0.023, and p < 0.001, respectively)." (PMID 36143057, 2022). "There was no recurrence of infection in either group; however, group B (i.e., novel technique) improved significantly faster in terms of WBC count and CRP level during the first period." (PMID 35241107, 2022). "In fact, in the control group without infection PCT increased slightly and transiently after CBP, while the increase in CRP was longer." (PMID 36555891, 2022). "For diarrhea reported symptoms, 42.4% of infants at 9 months had no indication of infection as indicated by CRP and AGP; for acute respiratory reported symptoms, 42.6% had no indication of infection." (PMID 36211493, 2022). "The purpose of our study was to evaluate the benefit of the plasma inflammatory markers WBC, CRP, and PCT for the diagnosis of VRI and its differentiation from patients with non-cerebral infection and patients without infection." (PMID 35547383, 2022). "Acute phase reactants such as C-reactive protein (CRP) and erythrocyte sedimentation rate (ESR), which are used as the markers of the systemic inflammatory response and are not specific for infection." (PMID 35801326, 2022). "Laboratory values, including the inflammatory markers, C-reactive protein, and erythrocyte sedimentation rate (ESR), are normal in the absence of infection signs." (PMID 36431079, 2022). "Additionally, the serum CRP level, which was agreed by the consensus meeting to have a threshold value of 100 mg/L for an acute periprosthetic infection, may attain this level in an early postoperative period in the absence of an infection." (PMID 36289943, 2022).
infection (continued). "While traditional biomarkers such as CRP and PCT are useful for excluding infection because they have high negative predictive accuracies, it is evident that they have relatively low positive predictive values." (PMID 34522543, 2021). "Higher WBC counts and higher percentage of neutrophil without infection are likely a result of a LPS-induced proinflammatory state with elevated LBP and CRP as well." (PMID 33753837, 2021). "CRP and WBC values were, for instance, normal in AHF patients without any infection, whereas they were significantly elevated in AHF patients with respiratory or other infection." (PMID 34947960, 2021). "Upon occurrence of a secondary infection, no significant increase in PCT and CRP levels was observed in the D+T− group (p = 0.052 and p = 0.08, respectively)." (PMID 34353339, 2021). "Although there were no overt signs of infection in our current cohort, the median WBC and CRP levels were increased." (PMID 34065096, 2021). "As opposed to CRP and SAP, PTX3 is rapidly synthesized and secreted at sites of infection/inflammation by a variety of immune and non-immune cells in response to TLR engagement, microbial moieties, and inflammatory cytokines." (PMID 34868070, 2021). "Our previous study showed that FIB was not inferior to ESR and CRP in differentiating PJI and aseptic loosening, and it was useful in assessing infection outcomes after first-stage surgery." (PMID 34030692, 2021). "Low serum inflammatory parameters such as C-reactive protein (CRP) and erythrocyte sedimentation rates (ESR) are false negative in a proportion of patients with a low-grade infection." (PMID 33559723, 2021). "We also observed that the inflammatory biomarkers CRP, IL6 and TNF-α were higher among patients who developed AKI compared to those who did not, which highlights the role of severe infection in the pathogenesis of AKI." (PMID 34577543, 2021). "Chronic inflammation is a consistently documented biological feature of aging, with biomarkers of inflammation such as C-reactive protein (CRP), interleukin-1B/6, and tumour necrosis factor alpha increasing with age, even in the absence of infection." (PMID 32586324, 2020). "However, they did not include DS stage, ANC or CRP in their univariate or multivariate analysis; the blood stream was the only discussed infection site; and patients received antitumour therapy, all of which may have caused the difference in risk factors in the final model between our studies." (PMID 32972385, 2020). "The recent study only focuses on the status of CRP and MDA without observing deeply for the infection status and the treatment history as well." (PMID 32695177, 2020). "CRP and AGP are positive acute phase proteins and their expressions increase rapidly during trauma and infection, while the expression of the negative acute phase protein, TRF, decreases." (PMID 32722717, 2020). "We objectively evaluated the time-to-infection-free duration (by serum CRP and ESR level) between the ASA group and non-ASA group and found a trend with benefit on infection resolution in the ASA group (p = 0.045)." (PMID 32994449, 2020). "The accuracy of traditional infection biomarkers (CRP and PCT) was low, and newly proposed biomarkers (SAA, NP) and ratios of CRP/NP and SAA/NP were not significantly better." (PMID 32997689, 2020). "Since the conformation of CRP is altered under inflammatory conditions and altered CRP binds to immobilized factor H also, we hypothesized that in order to protect against late-stage infection, CRP needed to change its structure and that was not happening in mice." (PMID 33117400, 2020). "A well-studied biomarker, C-reactive protein (CRP), is a sensitive and valuable nonspecific indicator of most forms of tissue damage, inflammation, and infection, reflecting a broad range of diverse pathologic processes." (PMID 32450789, 2020).
infection (continued). "Increased levels of infection-related biomarkers, including PCT (0.21 vs 0.06 ng/ml) and CRP (70.5 vs 7.2 mg/L) were found in non-survivors when compared with those of survivors (P < 0.001)." (PMID 32746940, 2020). "Other infection related markers, ESR, procalcitonin, CRP and LDH, was not significantly correlated with critical illness, after adjustment for age, gender and comorbidities." (PMID 33087114, 2020). "Compared with non-infection patients, SLE patients with infection had a significantly higher serum level of ESR, CRP, and PCT (all P<0.05), the mean Hb level of infection patients was significantly lower (P<0.05)." (PMID 30994732, 2019). "Both PCT (2.25 vs. 0.15 ng/mL, p = 0.000) and CRP (68.35 vs. 45.65 mg/dL, p = 0.008) were significantly higher in GPP patients with bacterial infection compared to those without infection." (PMID 31777354, 2019). "The acute phase protein, C-Reactive Protein (CRP), is a non-specific inflammatory marker related to both acute and chronic inflammation including infection, autoimmune reactions, malignancy, traumatic tissue damage and necrosis." (PMID 32082531, 2019). "The CRP in the EAP and E. coli groups was higher than that in the control and naïve groups 1 month after immunization or infection but not after 3 and 6 months." (PMID 31088536, 2019). "A study conducted by Reveille revealed that in AS patients in the inflammatory stage, inflammatory markers such as C-reactive protein (CRP), IL-6, and erythrocyte sedimentation rate (ESR) were often higher than normal values, while infection did not exist." (PMID 31395063, 2019). "They compared the patients with and without infection and observed that there were statistically significantly higher PCT and CRP levels in patients with infection." (PMID 31691767, 2019). "The remaining 11 patients with no positive microbiology culture result had abnormal CRP and WCC profiles along with clinical suspicion of infection and were each started on antibiotic therapy." (PMID 30250733, 2018). "IG percentage, CRP, ANC, and WBC were all significantly higher in SBI patients when compared with those without severe infection." (PMID 30344287, 2018). "In contrast, serum amyloid A (SAA) and C-reactive protein (CRP) were not reported in our work, while they were actually elevated in diseased rabbits with presumptive E. cuniculi active infection, Cray’s unpublished data]." (PMID 28723944, 2017). "Hence, although CRP would appear to be sufficient for infection detection by looking at its distribution, it presents two main issues: it is the least requested of all biomarkers in the culture-negative category (11%) and it does not provide any information regarding the location of the infection." (PMID 29216923, 2017). "The purpose of this study was to investigate the diagnostic value of the preoperative laboratory protocol including IL-6, WBC, CRP, and ESR in bone nonunion patients with suspected infection." (PMID 29130050, 2017). "With the eradication of the infection as evident by absence of symptoms and significant reducing trend of erythrocyte sedimentation rate (ESR) and C-reactive protein (CRP)." (PMID 29021886, 2017). "Kinetic studies demonstrated CRP levels elevate on post-operative day (POD) 1, peak from POD2 to POD3, and decline by POD5 provided that there is no complication or infection." (PMID 28484510, 2017). "In contrast, CRP and PCT levels on the first and third day after onset were significantly elevated in those SIRS patients with infection compared to those without infection (prange = < 0.001–0.001)." (PMID 28079172, 2017). "Apart from standard care, including physical examination and image studies, laboratory tests, such as white blood cell counts, erythrocyte sedimentation rate (ESR) and C-reactive protein (CRP), are not specific in differentiating disease flare or infection." (PMID 27096761, 2016).
infection (continued). "CRP, PCT and ICIS were increased on days 0–2 in patients with infection as compared to those without infection." (PMID 27384242, 2016). "Although an elevation in C-reactive protein (CRP) and/or erythrocytic sedimentation rate (ESR) should not be taken as pathognomonic for an infection, both serve as screening and surveillance tests in the diagnosis and treatment of spinal infections." (PMID 26496928, 2016). "In the literature, the sTREM-1 in the group without infection was usually near zero, which differed from PCT or CRP." (PMID 27096761, 2016). "Within days to weeks after birth, they had repeated episodes of systemic inflammation with diarrhea and elevated serum C-reactive protein (CRP) and white blood cell (WBC) and neutrophil count without evidence of infection." (PMID 27523608, 2016). "Therefore, we inferred that higher levels of BATF2 may reflect nonspecific host responses to infection, much like the acute-phase reactant, serum C‐reactive protein (CRP) that is widely used as a biomarker for infection and was also not significantly different between the 2 groups." (PMID 27734027, 2016). "When serum CRP level increases in SLE patients without elevation of the C4d/CR1 ratio, it is likely that the patients have only infections and not flare-up." (PMID 26273660, 2015). "In patients without infection LBP versus IL-6 at 3 d (P = 0.003) and IL-6 versus CRP at 3 d (P = 0.003) were significantly correlated." (PMID 25613713, 2015). "In patients without infection, marker levels significantly increased for LBP (6 h versus 24 h: P = 0.005, 6 h versus 3 d: P = 0.005, 6 h versus 7 d: P = 0.007) and CRP (6 h versus 24 h: P = 0.001)." (PMID 25613713, 2015). "Although patients with SLE relapse have an increased erythrocyte sedimentation rate (ESR), their CRP level does not robustly increase, whereas SLE patients with infection exhibit increase in both ESR and the CRP level." (PMID 26273660, 2015). "Patients with elevated CRP and ESR values were more likely to be infected at revision arthroplasty, with normal levels highly predictive of no infection." (PMID 26181332, 2015). "CRP concentrations and [CRP]/[BSA]-quotient did not express significant differences between infected and healthy animals or during the course of infection." (PMID 26209015, 2015). "In this short-term prognostic analysis, the three infection-screening markers commonly used in medical laboratories (WBC count, CRP and IL-6) were not chosen as candidate predictors of mortality." (PMID 24393388, 2014). "In particular, a considerable number of the patients with infections but no fever had no increases in (WBC count, CRP and IL-6)." (PMID 24393388, 2014). "Burns, regardless of the total body surface area burned (TBSA), induce significant elevations in the traditional biomarkers of inflammation, including CRP, TNF-a, IL-6, and PCT, even without the presence of infection." (PMID 27355024, 2014). "In absence of overt infection, eleven FD patients out of twenty-four (45.8%) presented with at least one marker of inflammation altered in serum (ESR or CRP, or α-1 and α-2 globulins)." (PMID 23841057, 2013). "We believe that TPBS is particularly useful in patients with underlying inflammatory disease or malignancy, because serological examinations such as CRP and ESR are not always reliable in the diagnosis of residual infection." (PMID 24024089, 2013). "Positive systemic signs of infection include leukocytosis, elevated CRP and ESR levels, and recent unexplained hyperglycemia; although unremarkable clinical tests do not exclude infection." (PMID 24098835, 2013). "Various combinations of IL-6, CRP and TNF-a can maintain sensitivities and negative predictive values above 90% for late-onset infection from presentation until 48 hours afterwards." (PMID 23869218, 2013). "In certain situations, especially to differentiate bacteremic from non-bacteremic infections, PCT was reported to be superior to CRP." (PMID 23547830, 2013).
infection (continued). "In non-specific infection, the mean CRP was 122.52 ± 84.74 mg/dL, ESR was 81.12 ± 24.32 mm/h and WBC was 10,329.4 ± 4,343/mm3, while postoperatively CRP was 22.69 ± 19.92 mg/dL, ESR was 46.65 ± 24.29 mm/h and WBC was 8,552.9 ± 5,012/mm3." (PMID 23558792, 2013). "After six weeks of an antibiotic cement spacer combined with systemic antibiotics, the infection was cleared, shown by normal erythrocyte sedimentation rate (ESR), C-reactive protein (CRP) and negative culture from aspiration." (PMID 20492692, 2010). "Even in the absence of overt infection or inflammation, many ESRD patients show increased levels of acute-phase proteins, such as C-reactive protein (CRP), ferritin, fibrinogen, and/or interleukin-6 (IL-6), associated with low serum albumin levels." (PMID 17206511, 2007). "Additionally, while PCT elevation was a significant indicator of bacterial growth, CRP and WBC values were not reliable for detecting infection." (PMID 41007066, 2025). "Unlike CRP, which may take hours to rise, MDW changes can occur rapidly, enhancing its value for early detection of infection." (PMID 40460177, 2025). "ICIS was superior to CRP and PCT in discriminating infection from no infection on day 1 in the ICU." (PMID 40471473, 2025). "However, required elements of the CAR HEMATOTOX score (eg, C-reactive protein, ferritin) had not been collected in the majority of CD30 CAR-T patients, and we were unable to investigate its ability to predict infection in CD30 CAR-T recipients." (PMID 40980578, 2025). "Furthermore, although an increase in PCT was a significant marker for bacterial growth, CRP and WBC levels were not definitive indicators of infection." (PMID 41007066, 2025). "However, this therapy can also lead to increases in CRP and PCT levels even in the absence of infection." (PMID 40806991, 2025). "Further, we evaluated NLR and CRP as markers of inflammation, but we did not explore cytokines or other markers of immune dysregulation, limiting the biological plausibility of the proposed EBI–infection–DCI pathway." (PMID 40507570, 2025). "Furthermore, maternal serum markers of infection (WBC count and CRP) in blood samples have not been evaluated in previous studies." (PMID 40807144, 2025). "In sepsis, PTX3 was reported to be superior to the classical biomarkers CRP and procalcitonin (PCT), probably due to the fact that it is locally produced at the site of tissue damage or infection, rather than relying on other molecules to trigger the synthesis of body organs." (PMID 40299501, 2025). "Another study found that inflammatory markers such as IL-6, C-reactive protein (CRP), ferritin, lactate dehydrogenase (LDH), and D-dimer were found to be highly elevated in severe and critical COVID-19 infection as opposed to mild infection." (PMID 40376340, 2025). "-22The baseline CRP and PCT levels can be elevated even in the absence of infection." (PMID 40521830, 2025). "With regard to the ‘classical’ combined infection predictors (temperature ≥ 38 °C; WBC ≥ 17 000/mm3 for children < 4 years old and ≥12 000/mm3 for ≥4 years old; ESR ≥ 20 mm/h; and CRP ≥ 10 mg/L), the distribution was not significantly different between SA of the hip and the knee." (PMID 40828529, 2025). "CRP, ESR, WBC, and IL-6 are not accurate enough to conclude that an infection is present or not, but they indicate there might be an infection and should be used as supplements to other outcome measurements." (PMID 39452605, 2024). "Therefore, IL-6 alone is an excellent predictor of postoperative infection without the need for combined PCT and CRP levels, eliminating the needless testing and saving the hospital expenses." (PMID 38504206, 2024). "Research had shown that when the infection rates of H. pylori were not significantly different between AMI patients and those with UA, the antibody titers of H. pylori and C-reactive protein (CRP) levels in AMI patients were significantly greater than those in UA patients." (PMID 39290976, 2024).